TCIRG1 (T cell immune regulator 1, ATPase H+ transporting V0 subunit a3)
Description:
Subunit of the V0 complex of vacuolar(H+)-ATPase (V-ATPase), a multisubunit enzyme composed of a peripheral complex (V1) that hydrolyzes ATP and a membrane integral complex (V0) that translocates protons (By similarity). V-ATPase is responsible for acidifying and maintaining the pH of intracellular compartments and in some cell types, is targeted to the plasma membrane, where it is responsible for acidifying the extracellular environment (By similarity). Seems to be directly involved in T-cell activation.
Synonyms: OC116; TIRC7; ATP6N1C; ATP6V0A3; OC-116; Atp6i; a3; OC-116kDa; OPTB1; Stv1; Vph1
Tractability: Antibody: its Gene Ontology location is reachable by antibodies, with high confidence; UniProt predicts a signal peptide or a membrane-spanning region. PROTAC: ubiquitination databases record sites on it; its protein half-life has been measured.
Gene: Protein-coding gene on chromosome 11 (68,039,025 to 68,050,895, forward strand). Ensembl gene ENSG00000110719.
Subcellular location: Membrane
Subcellular location (Human Protein Atlas): Mitochondria
Pathways (Reactome):
Immune System: Neutrophil degranulation; ROS and RNS production in phagocytes
Transport of small molecules: Ion channel transport; Transferrin endocytosis and recycling
Cellular responses to stimuli: Amino acids regulate mTORC1
Signal Transduction: Insulin receptor recycling
Gene Ontology:
Molecular function: protein binding; ATPase binding; proton-transporting ATPase activity, rotational mechanism
Biological process: cellular defense response; lysosomal lumen acidification; macroautophagy; ossification; positive regulation of cell population proliferation; protein catabolic process in the vacuole; proton transmembrane transport; vacuolar acidification
Cellular component: apical plasma membrane; lysosomal membrane; endosome membrane; ficolin-1-rich granule membrane; phagocytic vesicle membrane; plasma membrane; proton-transporting V-type ATPase complex; vacuolar proton-transporting V-type ATPase complex; late endosome; lysosome; membrane; nucleus; phagocytic vesicle; proton-transporting V-type ATPase, V0 domain; secretory granule membrane; vacuolar proton-transporting V-type ATPase, V0 domain
Genetic constraint (gnomAD): Loss-of-function variants: 85 observed, 83.33 expected, observed/expected ratio (o/e) 1.02, 90% interval 0.86 to 1.22. The upper end of that interval is the gene's LOEUF score, 1.22, which puts it in group 5 of 6, group 1 being the genes least tolerant of losing a copy. Missense variants: 1,069 observed, 1,083.1 expected, observed/expected ratio (o/e) 0.99, 90% interval 0.94 to 1.04. Synonymous variants: 499 observed, 465.61 expected, observed/expected ratio (o/e) 1.07, 90% interval 1 to 1.15.
Gene-disease validity (ClinGen):
ClinGen rates the evidence that TCIRG1 causes each of these diseases.
autosomal recessive osteopetrosis 1 (autosomal recessive): Definitive.
dysosteosclerosis (autosomal recessive): Limited. Dysosteosclerosis is a skeletal dysplasia characterized by progressive osteosclerosis and platyspondyly.
Homologues: Orthologues: chimpanzee TCIRG1 (99% identical), macaque TCIRG1 (97% identical), pig TCIRG1 (86% identical), dog TCIRG1 (86% identical), guinea pig TCIRG1 (86% identical), rat Tcirg1 (84% identical), mouse Tcirg1 (84% identical), zebrafish tcirg1b (57% identical), tropical clawed frog tcirg1 (57% identical), zebrafish tcirg1a (56% identical), Drosophila melanogaster Vha100-3 (34% identical). Paralogues in human: ATP6V0A2 (51% identical), ATP6V0A4 (47% identical), ATP6V0A1 (47% identical).
Diseases named in the same sentence as TCIRG1 in open-access papers:
TCIRG1 is named in the same sentence as 76 diseases in open-access papers, as found by Europe PMC text mining. Sharing a sentence is not in itself a finding about the gene and the disease. The quoted sentences say what the papers report.
osteopetrosis (42 papers, 2009 to 2025). Osteopetrosis, also known as marble bone disease, is a descriptive term that refers to a group of rare, heritable disorders of the skeleton characterized by increased bone density on radiographs. "Mutations in the Tcirg1 gene sequence have been associated with osteopetrosis by impairing lysosomal transport in osteoclasts." (PMID 40995561, 2025). "To answer this question, we analyzed SSCs and downstream progenitors from oc/oc mice, as the animal model of the most frequent subset of human recessive osteoclast-rich osteopetrosis associated with mutations in the TCIRG1 gene." (PMID 38971808, 2024). "TCIRG1 gene mutations underlie osteopetrosis, a rare genetic disorder impacting osteoclast function with consequent brittle bones prone to fracture, in spite of being characterized by increased bone density." (PMID 37107657, 2023). "TCIRG1 mutations commonly cause bone mineralization defects and the co-occurrence of osteopetrosis and rickets, because V-ATPase keeps a low pH for bone resorption in bones and for Ca2+ absorption in the stomach." (PMID 37373559, 2023). "A Tcirg1-deficient mouse shows the typical osteopetrosis phenotype of humans, including abnormal tooth eruption and morphology, skull abnormalities, increased bone mass, and a shortened life." (PMID 37373559, 2023). "Single amino acid changes in highly conserved areas of the TCIRG1 protein have been linked to autosomal recessive osteopetrosis and severe congenital neutropenia." (PMID 35573728, 2022). "Among V-ATPase subtypes, variants of the TCIRG1 gene, encoding for the osteoclast-specific a3 subunit of V-ATPase, are responsible for human recessive osteopetrosis and for more than 50% of human malignant infantile osteopetrosis." (PMID 36293046, 2022). "Autosomal Recessive 1 and Autosomal Recessive Malignant Osteopetrosis TCIRG1 is associated with disorders like osteopetrosis." (PMID 35573728, 2022). "In summary, this study provided additional proof-of-concept that EFS.hTCIRG1-LV constitutes an efficient and clinically applicable LV for use in the GT of severe osteopetrosis due to TCIRG1 deficiency." (PMID 33575431, 2021). "TCIRG1 encodes V-ATPase a3 subtype, and its mutation is responsible for human recessive osteopetrosis." (PMID 32790690, 2020). "Genetic studies implicate a critical role for subunits ATP6V1B2, ATP6V1C1, ATPV0D2, and ATP6V0A3 (TCIRG1) in osteoclast activity as relevant mutations lead to osteopetrosis." (PMID 30804932, 2019). "Our results, supported by SNP genotyping, Sanger sequencing, allele-specific PCR and bioinformatics have not only expanded the spectrum of TCIRG1 pathogenic variations but also the body of evidences supporting the role of a3 isoform in osteopetrosis." (PMID 29237407, 2017). "Osteopetrosis is frequently accompanied by osteomalacia or osteopetrorickets and this additional pathology is also found in 2-week-old Tcirg1-deficient oc/oc mice." (PMID 26346547, 2016). "Based on our own findings and reports on mice and humans with TCIRG1 mutations, we conclude that the Snx10 KD mice have a phenotype of osteopetrosis with super-imposed rickets: osteopetrorickets." (PMID 25811986, 2015). "The patient was diagnosed with osteopetrosis, which was confirmed due to mutation in the TCIRG1 gene [g.11279G>A(IVS18+1) paternal allele, g.8280_9560del (ex." (PMID 25330538, 2014). "The impaired bone resorption associated with osteopetrosis-causing TCIRG1 mutations might result from defects in vesicle trafficking or fusion in osteoclasts as well as defects in the proton-pumping function of V-ATPase." (PMID 37107657, 2023). "More than 50% of the cases of human malignant infant osteopetrosis are caused by TCIRG1 mutations." (PMID 37373559, 2023). "Osteopetrosis is characterized by increased bone density caused by decreased osteoclasts or dysfunction of their differentiation and absorption properties, usually caused by biallelic variants of the TCIRG1(OMIM:604592)and CLCN7(OMIM:602727) genes." (PMID 36999084, 2023).
osteopetrosis (continued). "Notably, TNSFR11A and TCIRG1 mutations are also reported in osteopetrosis, autosomal recessive 7 (OPTB7) and osteopetrosis, autosomal recessive 1 (OPTB1), respectively." (PMID 35812760, 2022). "We looked at TCIRG1’s nsSNPs to discover which ones were the most detrimental and could be linked to Osteopetrosis, congenital neutropenia, and other immune-related diseases in this study." (PMID 35573728, 2022). "Notably, TCIRG1 mutations cause overall severe form of osteopetrosis indicated by severe hematological manifestations requiring HCST treatment." (PMID 34753502, 2021). "Additionally, disease candidate gene sequencing via Sanger sequencing in further two families (OP5 and OP9) with osteopetrosis identified two homozygous variants, one each in TCIRG1 and CLCN7." (PMID 34753502, 2021). "More than 50% of human malignant infantile osteopetrosis is accounted for by TCIRG1 mutations." (PMID 32790690, 2020). "In this study, we derived and expanded iPSC lines successfully from osteopetrosis patients with mutations in TCIRG1, CLCN7 and SNX10 genes (accounting nearly 70% of all cases) using two different integration-free reprogramming methods under feeder-free culture conditions." (PMID 31315669, 2019). "However, malignant infantile osteopetrosis, a lethal form of the disease, is mostly (50%) caused by mutation(s) in TCIRG1 gene." (PMID 29237407, 2017). "Of note, mutations in CLCN7, CA2 and TCIRG1, disrupting the regulation of organelle pH and acid secretion, may cause osteopetrosis by affecting the osteoclast ability to dissolve the bone matrix." (PMID 27533615, 2016). "Various forms of recessive osteopetrosis have been reported, some of which are associated with the most severe phenotypes (including those caused by mutations in the TCIRG1, CLC7, and OSTM1 genes), whereas mutations in other genes (CAII and PLEKHM1) give a milder osteopetrotic phenotype." (PMID 23160729, 2013). "TCIRG1 is well-documented in bone disorders: mutations in TCIRG1, account for over 50% of infantile malignant autosomal recessive osteopetrosis cases, and its R740S mutation in mice disrupts proton pump function, inducing osteopetrosis and highlighting its key role in bone homeostasis." (PMID 40995561, 2025). "The patient was referred to our institution for potential bone marrow transplantation based on a presumed diagnosis of autosomal recessive TCIRG1-related osteopetrosis." (PMID 40385982, 2025). "In this paper, we exploited the murine model of Tcirg1-defective osteopetrosis to test the efficacy of ex vivo gene therapy, as well as to optimize the HSPC mobilization and pre-transplant conditioning, fundamental for a successful outcome of the GT protocol." (PMID 39314524, 2024). "Transfecting induced pluripotent stem cells (iPSCs) from oc/oc mice, which carry a deletion in the Tcirg1 gene and closely mimic the clinical features of human osteopetrosis, with a Bacterial Artificial Chromosome (BAC) containing the full-length Tcirg1 gene." (PMID 39392536, 2024). "Herein, we reported on four patients with osteopetrosis, in whom we identified compound heterozygous variants in the CLCN7 and TCIRG1 genes." (PMID 36999084, 2023). "These nsSNPs have been connected to their participation in the pathophysiology of TCIRG1-related illnesses such as osteopetrosis and congenital neutropenia." (PMID 35573728, 2022). "A number of studies have found a relationship between SNPs in the TCIRG1 gene and osteopetrosis and congenital neutropenia." (PMID 35573728, 2022). "Keeping a possibility of osteopetrosis, a targeted NGS was performed which revealed a homozygous variant in the exon 7 of the TCIRG1 gene." (PMID 34777883, 2021). "The AD, AR and XL forms of osteopetrosis are predominantly caused by mutations in the CLCN7, TCIRG1 and IKBKG genes respectively." (PMID 31888683, 2019). "To date, 11 osteopetrosis genes have been identified including 7 genes associated with ARO; TCIRG1, CLCN7, OSTM1, SNX10, TNFSFR11A, TNFSF11 and PLEKHM1." (PMID 29237407, 2017).
osteopetrosis (continued). "Homozygous mutations in the genes encoding the a3 subunit of V-ATPase (TCIRG1) and the CLCN-7 produce severe malignant osteopetrosis phenotypes in both humans and mice." (PMID 19232111, 2009). "In contrast to other gene defects described in osteopetrosis (TCIRG1, CLCN7), OSTM1 mutations are typically not curable by a curative hematopoietic stem cell transplantation because of their early and irreversible neurological involvement." (PMID 40625472, 2025). "Of these models, the oc/oc, Clcn7−/−, and gl/gl mice carry mutations in the genes with the highest incidence in human IMO (Tcirg1, Clcn7, and Ostm1, respectively) and thus most substantially facilitated study of the pathophysiology of the most severe forms of human osteopetrosis." (PMID 33575431, 2021). "TCIRG1 is involved in autophagosome assembly, and it is usually found relevant with osteopetrosis." (PMID 35237298, 2021). "We performed both SeV- and Epi5-mediated inductions from three patients who had disease-associated mutations in three different genes (TCIRG1, SNX10, and CLCN7) representing the diverse genetic heterogeneity of osteopetrosis phenotype and two healthy donors, under the same culture conditions." (PMID 31315669, 2019). "In this study, an affected girl with osteopetrosis was introduced who had no mutation in most common causative genes (TCIRG1, CLCN7 and OSTM1) for the disease, but analysis of SNX10 gene was able to detect a novel homozygous deletion in her." (PMID 29090071, 2017). "The identification of human genes associated with bone fragility started around the 1990s through the study of monogenic syndromes with marked skeletal phenotypes such as osteogenesis imperfecta due to COL1A1 and COL1A2 defects and osteopetrosis due to TCIRG1 defects." (PMID 27533615, 2016). "Indeed, RANK-dependent patients received HSCT later in life, owing to a milder hematological involvement, compared with classic TCIRG1-dependent osteopetrosis." (PMID 22271396, 2012). "Furthermore, Tcirg1-/- mice have significant osteopetrosis and die within 5 weeks." (PMID 32790690, 2020). "The spectrum of CLCN7-related osteopetrosis includes infantile malignant CLCN7-related ARO, IAO and ADOII.CLCN7 (13%–16%) and TCIRG1 (51%–53%) are the major obligate genes responsible for ARO." (PMID 36999084, 2023). "HSCT is also used to treat genetic abnormalities in CLCN7, TCIRG1, SNX10, and TNFRSF11A leading to osteopetrosis." (PMID 33350578, 2021). "Mutations in genes TCIRG1, CLCN7, OSTM1, SNX10 and PLEKHM1 lead to osteoclast rich osteopetrosis, which has abundant but nonfunctional osteoclasts." (PMID 34753502, 2021). "The most commonly affected genes of osteopetrosis are CLCN7 and TCIRG1." (PMID 26346547, 2016).
autosomal recessive osteopetrosis (18 papers, 2010 to 2026). An autosomal recessive form of osteopetrosis caused by mutation(s) in at least 8 genes related to osteoclast function. "Biallelic loss-of-function mutations of TCIRG1 are the major cause of infantile malignant osteopetrosis (IMO) (OMIM 259700), a lethal autosomal recessive disorder with secondary hematological and neurological abnormalities." (PMID 40964614, 2025). "TCIRG1 is best known for its role in osteoclast function and bone resorption, with loss-of-function mutations linked to autosomal recessive osteopetrosis (ARO)." (PMID 40964614, 2025). "TCIRG1 encodes a subunit of a vacuolar H+-ATPase, which acts as a proton pump, and the variations in this gene are associated with autosomal recessive osteopetrosis and dominant severe congenital neutropenia." (PMID 41383606, 2025). "Mutations in the T cell immune regulator 1 (TCIRG1) gene, which impair OC resorptive activity, are responsible for autosomal recessive osteopetrosis." (PMID 39392536, 2024). "Among the 46 patients without a clinical suspicion of monogenic bone disorders, one (NS2) was identified with a heterozygous c.2008C > T (p.Arg670*) variant in TCIRG1, a gene responsible for autosomal recessive osteopetrosis." (PMID 37076969, 2023). "We present male siblings with autosomal recessive osteopetrosis due to biallelic variants in TCIRG1 who survived childhood and underwent hematopoietic stem cell transplant (HSCT) in adulthood." (PMID 35720663, 2022). "We evaluated an adult patient with autosomal recessive osteopetrosis due to TCIRG1 variants by DXA and HRpQCT 11 years after HSCT." (PMID 35720663, 2022). "An adult male with autosomal recessive osteopetrosis due to variants in TCIRG1 underwent hematopoietic stem cell transplant in adulthood." (PMID 35720663, 2022). "Approximately 50% of the patients with recessive infantile malignant osteopetrosis have mutations to a3 subunit of V-ATPase protein complex, encoded by TCIRG1 gene." (PMID 29237407, 2017). "Alternative splicing mutations have also been reported in other bone diseases, such as in TCIRG1-linked autosomal recessive osteopetrosis, however the present study is the first to investigate AS in OCs in PDB." (PMID 25115182, 2014). "Mutations in the Tcirg1 (also known as Atp6V0a3) locus, which encodes the a3 subunit of V-ATPase, cause severe autosomal recessive osteopetrosis (ARO) in humans." (PMID 20711468, 2010). "More than half of all autosomal recessive osteopetrosis patients had TCIRG1 mutations." (PMID 35573728, 2022). "Our group demonstrated the potential of this approach using a murine model of autosomal recessive osteopetrosis (ARO) carrying a homozygous mutation in T cell immune regulator 1 (Tcirg1), the most frequently mutated gene in this disease, which encodes a subunit of the V-ATPase proton channel." (PMID 35159366, 2022). "As TCIRG1 encodes the osteoclast-specific 116-kD subunit of the vacuolar proton pump and its defect is responsible for a subset of human autosomal recessive osteopetrosis, TCIRG1 could be regarded as the potential targets for KIRC metastasis, especially to skeletal metastasis." (PMID 31681747, 2019). "Partial loss of ATP6V1H function can lead to osteoporosis/osteopenia, and mutations in T-cell immune regulator 1 (TCIRG1), also known as V-ATPase V0 subunit A3, which is responsible for secreting acid, cause autosomal recessive osteopetrosis in humans." (PMID 34054735, 2021). "TCIRG1-mediated IMO, also known as autosomal recessive osteopetrosis (ARO), is a very rare pediatric disorder that confers significant morbidity and mortality during the first decade of life." (PMID 33575431, 2021). "Four of the known ARO genes, TCIRG1, CLCN7, OSTM1 and SNX10 are significantly expressed in ruffled border of mature osteoclasts and are largely known for their involvement in autosomal recessive osteopetrosis." (PMID 29237407, 2017).